MMP9 (matrix metallopeptidase 9)
Diseases named in the same sentence as MMP9 in open-access papers (continued):
Sharing a sentence is not in itself a finding about the gene and the disease.
periodontal disease (continued). "Because of terchebulin and some crude extracts acting on P. gingivalis bacteria and MMP-9 enzyme that would make them promising natural preference for preventing and treating periodontal diseases." (PMID 28427461, 2017). "Several MMPs have been detected in their different enzymatic forms in gingival tissue, gingival crevicular fluid (GFC), saliva, and mouth rinse, with MMP-8, MMP-13, and MMP-9 as the main proteases involved periodontal disease destruction." (PMID 28218665, 2017). "MMP-8 and MMP-9 are the most abundant MMPs in periodontal tissues reflecting periodontal disease severity, progression, and treatment response." (PMID 28218665, 2017). "MMP-9 is a protease often found elevated in patients with periodontal disease and oral cancer; whereas MPO, a peroxidase often used as a measure of neutrophil degranulation, is elevated in diabetic patients." (PMID 24915044, 2014). "Proteolytic enzymes released by host cells are associated with tissue destruction in periodontal diseases, specifically MMP-2 and MMP-9 have been implicated in periodontal disease progression." (PMID 23843954, 2013). "The neutrophils are the major cells responsible for release of MMP and more importantly MMP-8 (collagenase-2) and MMP-9 (gelatinase-B) which is a concern to a periodontist as it is released during acute stages of periodontal disease." (PMID 24490073, 2013). "Our study is innovative because it demonstrated a reduction in the formation of MMP-2 and MMP-9 in an experimental model of periodontal disease." (PMID 23843954, 2013). "In fact, the suppression of excessive MMP-9 via elevated IL-37 levels might be an interesting new therapeutic approach in periodontal diseases." (PMID 40281482, 2025). "Rosacea diagnosis was the main factor associated with elevated MMP-9, independent of periodontal disease, smoking, or age." (PMID 41373451, 2025). "Moreover, auraptene inhibited the Porphyromonas gingivalis bacterial infection which causes periodontal diseases by reducing the secretion and activity of MMP-8 and MMP-9." (PMID 37447286, 2023). "Because of this, prior to treatment, patients with periodontal disease had MMP-9 values that differed significantly depending on the angle class (PD group: p = 0.005; POD group: p = 0.003); this effect was more pronounced in patients with angle class II/1 and II/2." (PMID 33498206, 2021). "The exact mechanism of involving MMP-9 in intracellular signaling is unknown, but both MMP-8 and MMP-9 are markers of apical and periodontal disease." (PMID 32467797, 2020). "However, this pattern of expression is contradictory to what has been published, since MMP9 is the most abundant in tissues affected by periodontal disease." (PMID 32867386, 2020). "A question on the periodontal disease status of those patients was not included, although periodontal disease and kidney disease are highly associated and periodontal disease is alone associated with increases in MMP-9." (PMID 26538831, 2015). "Periodontal disease characteristically exhibits high levels of salivary IL-8, MMP-9 and IL-1β." (PMID 24915044, 2014). "Tissue destruction caused by MMP-2 and MMP-9 was reduced in animals treated with 5 mg/kg AZT, indicating that IL-10 may be a protective cytokine in periodontal diseases." (PMID 24819928, 2014). "In addition, the in vitro MMP inhibition assays were carried out with MMP-9 (92 kDa gelatinase) and MMP-13 (collagenase-3), both known to be associated with periodontal disease and other conditions of connective tissue loss." (PMID 24453415, 2013). "Dysregulation of myocardial metalloproteinases (MMPs) is now regarded as an early contributing factor to the initiation and progression of heart failure and pre-treatment with Carvedilol prevented MMP-2 and MMP-9 expression shown to be activated in periodontal disease." (PMID 23843954, 2013). "Also, MMP-9 can be useful as a periodontal disease biomarker." (PMID 38474009, 2024).
periodontal disease (continued). "In addition, significant associations were found between MMP-8 and MMP-9 activities in gingival crevicular fluid and the severity of the periodontal disease, together with negative correlations with TIMP-1 and TIMP-2 levels." (PMID 37371608, 2023). "However, their major contribution to the prediction of caries was not to be expected, as the proteases MMP-8 and MMP-9 are part of a highly complex “protease web”, which is mainly associated with destructive periodontal disease." (PMID 33806927, 2021). "Among these, MMP‐9 and tumour necrosis factor (TNF) have been extensively studied for their involvement in the pathogenesis of periodontal disease." (PMID 40913361, 2026). "Gelatinase B, MMP-9, is a member of a subfamily of MMPs that degrades collagen and is one of the most abundant MMPs in periodontal tissues reflecting periodontal disease severity." (PMID 40281482, 2025). "Several studies showed elevated levels, in Gingival Crevicular Fluid (GCF), of MMP-9 and MMP-8 in patients with periodontal disease, and these molecules have been suggested to be valid indicators of the disease and have been observed for 2 months." (PMID 39350180, 2024). "MMP-9 is synthesised mainly by macrophages and neutrophils and is used in MMP-mediated destructive periodontal disease." (PMID 39350180, 2024). "An increase in the concentrations of salivary and serum MMP-9 and decrease in levels after periodontal therapy was demonstrated in several other studies, indicating the role of MMP-9 in periodontal diseases." (PMID 35408573, 2022). "Given that numerous studies have shown an increased expression of MMP-9 and MMP-8 activity in patients with periodontal disease, they have been proposed as valid indicators of the disease." (PMID 35163727, 2022). "Matrix metalloproteinase-9 (MMP-9) has been shown to play a key role in endothelial function and perhaps pivotal in the correlation between periodontal disease and cardiovascular disease (CVD)." (PMID 33810003, 2021). "The levels and especially activation of MMP-8, MMP-9, and MMP-13 have been shown to be correlated with active stages of periodontal disease, and they decrease to levels found in periodontally healthy GCF after conventional periodontal treatment." (PMID 30669541, 2019). "On the other hand, biomarkers of periodontal disease progression in GCF alone (MMP-8, MMP-9, Osteoprotegerin, C-reactive Protein and IL-1β) provided low sensitivity and high specificity values of 23% and 95%, respectively." (PMID 31817894, 2019). "MMP9/NGAL complex was revealed in GCF of patients with periodontal disease and accumulation of bacterial plaque as having a stronger expression and correlation with myeloperoxidase (MPO) than 92 and 82 kDa forms of MMP9." (PMID 24967433, 2014). "Worth mentioning, in periodontal diseases, dynamic changes in the level of LPS and consequently cytokines such as IL-1 beta and TNF-alpha results an increased level of the collagen degrading enzymes MMP-9." (PMID 40281482, 2025). "This suggests that MKE might have potential to treat periodontal disease by inhibiting collagenases (MMP-1, -8, -13), gelatinase (MMP-9), and stromelysin (MMP-3)." (PMID 36661522, 2023). "It has also been reported that the level of MMP-9 in GCF and in periodontal ligament is increased in the course of periodontal disease and that it may be reduced by effective periodontal therapy." (PMID 36297241, 2022). "The ROC curves for MMP-8 and MMP-9 indicated they were not significant periodontal disease biomarkers (p = 0.921 and p = 0.89, respectively)." (PMID 35562715, 2022). "The amount of IL-1, IL-8, MMP-8, MMP-9, and MMP-13 in saliva samples from patients with periodontal disease and healthy controls have been analyzed and compared, and one study compared hemoglobin levels in blood samples with biomarkers in saliva samples from patients with periodontal disease." (PMID 34199256, 2021).
periodontal disease (continued). "Salivary biochemical markers, which are characteristic for periodontal disease, include enzymes (MMP-1 (matrix metalloproteinase-1), MMP-8 (matrix metalloproteinase-8), MMP-9 (matrix metalloproteinase-9), immunoglobulins, and a group of proteins (albumin, fibronectin)." (PMID 32598403, 2020). "IL-8 and MMP-9 in saliva correlated positively with periodontal disease as assessed by gingival bleeding in non-smokers." (PMID 25155252, 2014). "Extracellular metalloproteinases (MMPs), especially 8 and 9 (MMP-8 and MMP-9), play a major role in periodontal destruction, being observed at significantly higher levels in the gingival crevicular fluid (GCF) of patients with periodontal disease compared to healthy individuals." (PMID 41440322, 2025). "In addition, salivary IL-8 and MMP-9 were positively correlated with periodontal disease, as assessed by gingival bleeding in nonsmokers." (PMID 37762876, 2023). "Although these findings raise the possibility that MMP-9 and IL-8 may be involved in both periodontal disease and COPD, the results differ between smokers and nonsmokers, and further investigations are needed." (PMID 37762876, 2023). "The MMP9/NGAL complex was revealed in systemic diseases and in GCF of patients with a poor control of the bacterial plaque with periodontal disease but not during orthodontic treatment." (PMID 24967433, 2014).
heart failure (89 papers, 2007 to 2025). Inability of the heart to pump blood at an adequate rate to meet tissue metabolic requirements. "Accordingly, in human patients with MI, raised MMP9 expression and the associated cardiac remodelling are associated with an increased risk of developing heart failure and complications, resulting in poor prognosis." (PMID 39596076, 2024). "Spironolactone treatment has been shown to reduce MMP2 and MMP9 levels in patients at risk of heart failure." (PMID 36749631, 2023). "Clinical studies have also shown that MMP-9 is an independent risk factor for heart failure after acute MI." (PMID 35898278, 2022). "Episodes of ventricular tachyarrhythmia, potentially involved in sudden cardiac death, were associated with higher MMP‐9 levels, and particularly MMP-9/TIMP‐1 ratios in heart failure patients." (PMID 31932967, 2021). "Matrix metalloproteinase 9 (MMP9) is a biomarker associated with collagen degradation to cause heart failure." (PMID 34778271, 2021). "Heart histological staining and mRNA levels of genes associated with heart failure (Acta1 and Nppa), inflammation (IL‐6), and fibrosis (Ctgf, Col1a2, Timp1, and Mmp9) were assessed." (PMID 32133617, 2020). "Of these, IL6, MMP2, and MMP9 are established risk correlates and mediators of adverse myocardial remodeling in heart failure." (PMID 30089854, 2019). "The aim of the study was to assess the occurrence of classic risk factors in the study group of patients with heart failure and to link them with the transcriptional activity of the examined genes: metalloproteinase 9 (MMP-9) and the tissue inhibitor of metalloproteinases 1 (TIMP-1)." (PMID 38540214, 2024). "Even the transcriptional activity of MMP9 is associated with the severity of heart failure." (PMID 38660518, 2024). "In our present study, the higher dose of P234 increased the expression of inflammatory (Tnf), fibrotic (Ctgf, Tgfb, and Col3a1), heart failure (Nppa), and cardiac remodeling-associated (Mmp9) genes compared to the CKD-only group, supporting our echocardiographic and histology results." (PMID 37640761, 2023). "Heart failure may be caused by myocardial infarction by upregulation of the levels of MMP‐9 and anti‐angiogenic factors." (PMID 36478328, 2023). "Activation of MMPs, especially the gelatinases MMP-2 and MMP-9, is associated with adverse remodeling and LV dilatation in heart failure patients, and precedes LV dysfunction in animal models with tachycardiomyopathy, suggesting that they are early markers of cardiomyopathy." (PMID 34052857, 2021). "In addition, mmp9 is associated with a variety of cardiovascular diseases, e.g. idiopathic atrial fibrillation, aortic aneurysms And heart failure." (PMID 32321550, 2020). "Somuncu and colleagues showed that patients with MI who had MMP-9 plasma levels above 12.92 ng/mL at the time of hospital admission had 3.5-fold higher odds for cardiovascular mortality and increased risk for advanced heart failure compared to the group with lower MMP-9 concentrations." (PMID 33805901, 2021). "Another study, which explored the potential significance of MMP and TIMP levels in the blood of adult patients with heart failure, found that MMP-9, along with MMP-2 and TIMP-1, serves as a mortality predictor." (PMID 39466144, 2025). "qRT-PCR results indicated that MI significantly increased the mRNA levels of fibrosis-related genes (Col1, Col3, Mmp2, and Mmp9) and heart failure biomarkers (Anp, Bnp, and β-Mhc) compared to the sham group (p < 0.05 for all)." (PMID 39834616, 2025). "The effect of MMP-9 ablation should be studied in relation to dysregulated mitophagy during heart failure to determine if it helps with the cardiomyocyte death seen in HFrEF and if it helps preserve ejection fraction transition to reduced ejection fraction." (PMID 39201469, 2024). "Is the ablation of the MMP-9 gene effective in halting the transition from preserved ejection fraction to reduced ejection fraction during heart failure?" (PMID 39201469, 2024).
heart failure (continued). "Our results find further support in the decreased levels of antioxidant SOD3 and increased expression of MMP9, both established markers of heart failure." (PMID 38824159, 2024). "With the advancement of heart failure (decrease in left ventricular ejection fraction), an increase in the transcriptional activity of the metalloproteinase 9 (MMP-9) gene was found." (PMID 37893149, 2023). "Standard pharmacotherapy can help with this, as several drugs used to treat heart failure and other conditions show activity against MMP-9." (PMID 37893149, 2023). "Upregulated genes in Vehicle include NPPB, COL1A1, FMOD, LOX and MMP9, among others, some of which are related with pro-fibrotic processes and heart failure." (PMID 37342444, 2023). "An increase in COL1A expression level in the heart is involved in the onset or progression of cardiac fibrosis; in addition, MMP9 regulates cardiac function, and MMP9 disruption results in cardiac failure." (PMID 36269775, 2022). "In addition, enhanced activation of MMP9 was associated with the state of active myocardial remodeling and could be a potentially useful marker for the identification of patients at risk for heart failure development and poor outcome." (PMID 35321732, 2022). "Increased activity of MMP-9 is found in the heart failure rat model and the myocardium of patients with heart failure, which affects the heart function of patients with CHF." (PMID 35035498, 2022). "MMP-2 and MMP-9 are key regulators of LV remodeling and were upregulated both in MI and heart failure." (PMID 35898278, 2022). "TIMP-2 has the specific ability to stimulate collagen synthesis, and MMP-9 seems to be more activated in heart failure with reduced ejection fraction and dilated cardiomyopathies than MMP-2." (PMID 36005418, 2022). "Higher circulating MMP‐9 and TIMP‐1 levels and MMP-9/TIMP‐1 ratios were reported in ischemic cardiomyopathy and are associated with disease severity in heart failure and tissue remodeling in myocardial hypertrophy." (PMID 31932967, 2021). "Disparity between TIMP‐1 and MMP‐9 levels was also shown to contribute to adverse events and mortality in heart failure patients." (PMID 31932967, 2021). "TNF-α, MMP-2, and MMP-9 act on inflammatory processes, are upregulated during heart failure (HF), and influence ventricular remodeling." (PMID 33441969, 2021). "Further logistic regression analysis showed that except MMP-9, the biomarkers sST2 (OR = 1.960), MMP-2 (OR = 0.805) and NT-proBNP (OR = 0.002) were all independent risk factors for patients with heart failure." (PMID 32354356, 2020). "Heart-failure induction by isoprenaline resulted in an increase in the circulating MMP9 (15.85 ± 0.57 ng/ml), and the increase was significant statistically (P > 0.05) when compared to the control group (9.91 ± 0.43 ng/ml)." (PMID 31053170, 2019). "sacubitril in combination with aliskiren or with ramipril have effectively reduced plasma-cardiac biomarkers such as CK-MB, MMP9, and NT-proBNP in rats with heart failure." (PMID 31053170, 2019). "We propose MMP-9 as a potential biomarker of late fibrosis, where cardiac remodeling results in heart failure, apical aneurysm of the left ventricle, and hypertrophy." (PMID 31578449, 2019). "Sacubitril in combination with aliskiren or with ramipril effectively reduced plasma cardiac biomarkers, such as CK-MB, MMP9, and NT-proBNP, in rats with heart failure." (PMID 31053170, 2019). "Both, the effect of MMP-9 and angiostatin on NO synthesis and on a possible transition to decompensated heart failure in FC should be addressed in future studies." (PMID 30159316, 2018). "Together with changes of cardiac function, it has been shown that TIMP-1 interacts with MMP-2 and MMP-9 in patients with heart failure." (PMID 26495844, 2015).